IL6 (interleukin 6)
Diseases named in the same sentence as IL6 in open-access papers (continued):
Sharing a sentence is not in itself a finding about the gene and the disease.
cancer (continued). "IL-6 is known to be produced by cancer, immune, and stromal cells and is considered a significant player in cancer chemoresistance." (PMID 38562556, 2024). "Interleukins, particularly IL-6 and IL-8, have been shown to be upregulated in co-cultures of ASCs with various cancer cell types, including breast, colon, melanoma, and squamous cell carcinoma." (PMID 39519109, 2024). "Our data further underscore the role of IL-6 in cancer cell proliferation and migration, and therefore can be used as a molecular clue for the development of more efficient anti-cancer therapeutics." (PMID 38715108, 2024). "Interleukin 6 (IL-6) in the TME can induce cancer cell proliferation and angiogenesis and produce drug resistance." (PMID 38542707, 2024). "The presence of BM-MSCs in HNSCC-derived secretory molecules increased the migration of MSCs towards cancer cells and their invasion, while these were reduced by the inhibition of IL-6 and PDGFR-α." (PMID 39120301, 2024). "Taken together, we can infer that both IL-6 and IL-17 can have a significant effect on supporting cancer cell survival during later stages of development." (PMID 38279220, 2024). "For example, patients with cancer might have poor appetite due to cytokine inhibition of neuropeptide Y. On the other hand, supplementation with n-3 PUFAs can decrease the production of interleukin-1 and interleukin-6 cytokines, then may combat the loss of appetite in these patients." (PMID 38281014, 2024). "In the search for a model to further explore regulation of IL-6 synthesis, PBMCs from cancer patients were found to produce large amounts of IL-6 in short-term cultures with autologous serum in the medium." (PMID 39518029, 2024). "There are also multiple clinical trials to assess the benefit of IL6 antagonism in addition to ICI for cancer therapy with the aim of preventing or mitigating ICI toxicities (NCT04258150, NCT04940299, NCT03999749)." (PMID 39737191, 2024). "TGFβ, however, by increasing IL-6 and MCT4, as well as down-regulating Cav1, is known as the most important cytokine contributing to carcinoma-associated fibroblast differentiation." (PMID 38361760, 2024). "Aggressive carcinomas develop only in the presence of additional mutations, such as abnormal expression of ERG, loss of IL-6/STAT3 functionality, dysfunction of the methyltransferase Kmt2c or activation of the RAS/MAPK cascade." (PMID 38811984, 2024). "We theorized that the CAF-secreted IL-6 functions in a paracrine manner to induce GM-CSF expression and secretion from carcinoma cells." (PMID 39199680, 2024). "Here, we extend existing modeling frameworks to build a quantitative, computational model for a specific therapeutic target: antibodies targeting the IL-6 and IL-8 receptors for the prevention of cancer metastasis." (PMID 38187701, 2023). "Elevated levels of IL-6 have been documented in aging, cancer progression, and the development of cancer cachexia." (PMID 37213604, 2023). "Our findings suggest that IL-6 serves as a cell-extrinsic factor secreted by cancer cells in response to genotoxic treatments to counteract the anti-survival and -metastatic activities of these anticancer agents." (PMID 37696858, 2023). "Interleukin-6 (IL-6) is another well-studied cytokine known to play an important role in cancer cachexia progression." (PMID 37998333, 2023). "Coincidently, this observation aligns well with the IL-6 expression and inflammatory milieu in cancer." (PMID 36845732, 2023). "IL-6 was also found to induce cachexia in cancer patients by altering the metabolism of lipids and proteins." (PMID 38003396, 2023). "There are additional antibodies targeting IL-6, which are currently undergoing preclinical trials in cancer, such as MED15117, clazakizumab, olokizumab, and sirukumab." (PMID 38313431, 2023). "In this scenario, interleukin-6 (IL-6), a pro-inflammatory cytokine, that was often found elevated in advanced cancers including STS, can reduce gut iron absorption resulting in blood Hb drop." (PMID 37637412, 2023).
cancer (continued). "For instance, BRD4 was required for IL-6-stimulated and Notch1-induced cancer migration in a triple-negative breast cancer model, indicating that BRD4 linked microenvironment inflammation to cancer propagation." (PMID 36627707, 2023). "There have been several reports on the prognostic significance of plasma IL-6 in ICI-treated patients with various cancers, including NSCLC." (PMID 38469154, 2023). "Macrophage stimulation by cancer cell-secreted interleukin 6 (IL6), macrophage colony-stimulating factor (M-CSF), and PGE2 triggers their polarization into the M2 subtype." (PMID 38020914, 2023). "Co-culture of MCF-7 cells on murine stroma induced the secretion of IL-6 and IL-8 by stromal cells exclusively, demonstrating a feed-forward stimulation mechanism for cancer cell growth once reactivation is initiated." (PMID 37296983, 2023). "IL-6, a pro-tumorigenic cytokine, has been suggested to be involved in cancer initiation and rapid progression through potentiating VEGF." (PMID 36357631, 2023). "Mediators of systemic inflammation, such as nitric oxide, prostaglandins, or cytokines (IL-1β and IL-6), also modify gene expression profile through the activation of DNA methyltransferases (DNMTs) and HDACs, thereby influencing the behavior of cancer cells." (PMID 37190141, 2023). "Inflammatory cytokines, including TNF-α and IL-6, are responsible for cancer cachexia and are relevant to adipocyte transformation." (PMID 36672449, 2023). "IL-8 probably affects cancer stem cells indirectly via progranulin and IL-6, whereas progranulin and IL-6 can affect cancer stem cells both directly via sortilin and indirectly via associated proteins." (PMID 38136303, 2023). "Further studies showed that the tested materialsinduced the expression of proinflammatory interleukins IL6 and IL8in normal cells, but their overexpression in the cancer cell lineresulted in cytostatic effects and proliferation reduction." (PMID 37867722, 2023). "Our study highlighted the critical contribution of IL-6 to the dynamic interaction between CAFs and cancer cells in the TME." (PMID 36635302, 2023). "Metavert treatment further downregulates procancer cytokines like IL-6 and IL-4, induces cancer cell apoptosis, and attenuates the expression of cancer stem cell markers, as well as impedes cancer growth and metastases." (PMID 37444617, 2023). "Further, secretion of the pro-inflammatory cytokine IL-6 from cancer cells was elevated with the incubation of PPMP for 12 hours." (PMID 37069244, 2023). "Taken together, these results indicated that compound 25 inhibited the constitutive and IL-6-induced pY705-STAT3 in cancer cells." (PMID 37240202, 2023). "(2020) evaluated that Rb1 can reduce the expression levels of key inflammatory cytokines TNF-α and IL-6 in a cancer cachexia mouse model, this finding is consistent with our experiment, indicating that Rb1 can alleviate symptoms caused by inflammation." (PMID 37868069, 2023). "The IL-6- and TNFR2-associated pathways are emerging as critical mediators of inflammation-associated cancers, including ovarian malignancy." (PMID 36765633, 2023). "There are data on the inhibition of the synthesis of TGFβ, TNFα, IL-6, and IL-1β by progestins in cancer cells." (PMID 37298830, 2023). "Therapies directed at targeting interleukin-6 have been observed to enhance outcomes across various types of cancer." (PMID 37892997, 2023). "IL-6 also maintains the migratory and invasive abilities of cancer cells to hamper the anti-metastatic activities of genotoxic agents." (PMID 37696858, 2023). "It is widely reported that the elevated level of IL-6 is related to the poor prognosis and drug resistance of various cancers." (PMID 36859398, 2023).
cancer (continued). "Cancer cells and CAFs secrete IL-6 to induce HIF-1α expression that modulates downstream genes responsible for chemotherapeutic resistance in cancer cells." (PMID 37627173, 2023). "By checking the signaling network between CAFs and cancer cells, IL6 signaling was found to be of significance." (PMID 37658364, 2023). "Monoclonal antibodies targeting IL-6 or relevant receptors have been shown to be effective in the treatment of numerous autoimmune and inflammatory diseases and are now being tested in cancer in combination with other cancer drugs." (PMID 38136303, 2023). "IL-6, akin to C-reactive protein, is gaining prominence as a biomarker in monitoring inflammatory responses, particularly in cases of cancer, infections, or autoimmune disorders." (PMID 38162646, 2023). "Although the relationship of -174G>C SNP in the IL-6 gene to various cancers has been evaluated, these results are contradictory." (PMID 38024543, 2023). "Based on our findings and taking into consideration previous studies showing the protumor effects of IL-6 and G-CSF, we further investigated the role of these proinflammatory mediators in cancer dormancy escape." (PMID 37699010, 2023). "IL-6 has been found to have stimulatory effects on cancer cells due to its signaling in numerous pathways that promote the cell cycle and proliferation." (PMID 36771154, 2023). "Our findings so far show that three of the peptides SPEA agonists have similar profiles of the full superantigen SPEA in activating the T- cells and producing different types of cytokines with an anti-cancer effect such as IL-1, IL-6, and IL-10." (PMID 37445686, 2023). "Together, these results suggest that lactate from cancer cells stimulates CAFs to produce IL-6, synergistically impairing the functions of cytotoxic lymphocytes." (PMID 37733442, 2023). "IL-6 is a tumorigenic driver, an anti-apoptotic signal, and a pivotal biomarker in cancer diagnosis and prognosis." (PMID 37753372, 2023). "The cytokines IL-6 and IL-10 are important for Th2-mediated function in cancer progression and exhibited reduced levels in the low-dose SNAP treatment group." (PMID 36639681, 2023). "Galectin-3 in cancer patients induces secretion of IL-6, G-CSF, sICAM-1 and GM-CSF from blood vascular endothelial cells in vitro and in mice." (PMID 38144531, 2023). "The serum concentration of IL6 reached peak levels in both groups, with an eight-fold increase observed in cancer patients when compared to the preoperative level and twice increased concentrations in patients with benign pancreatic diseases." (PMID 37610509, 2023). "Simultaneously, IL-6/STAT3 signaling in malignant EMT leads to the acquisition of cancer stemness in cancer cells; self-renewal and population expansion of CSCs need STAT3 in collaboration with stem-cell-associated transcription factors." (PMID 37373393, 2023). "Therefore, reducing IL-6 levels may contribute to decreasing the risk of cancer." (PMID 37381018, 2023). "First, cancer cells stimulate an innate and aspecific response mediated by IL-1, IL-6, and TNF-alpha production; this kind of response mainly stimulates macrophages and neutrophil granulocytes to attack the tumor cells." (PMID 36900413, 2023). "Inflammatory cytokines such as IFN-gamma, IL-1b, IL-2, IL-4, IL-6, IL-10, IL-12p70, and TNF-alpha have been shown to be involved in the immune response associated with cancer progression." (PMID 37373957, 2023). "Interleukin 6 is a main component that is ubiquitously found and known to be dysregulated in cancer." (PMID 37987305, 2023). "Cancer-mediated factors, including activin A and IL-6, would trigger BMP inhibitor Noggin expression in the muscle, leading to the inhibition of BMP activity in muscle fibers and motor nerves." (PMID 37217930, 2023). "STAT4 increases cancer-associated fibroblasts (CAF) that supports the production of CXCL12, IL-6 and VEGF and promotes the metastasis of ovarian cancer." (PMID 37680708, 2023).
cancer (continued). "IL6 can be produced by fibroblasts, monocytes/macrophages, B cells, T cells, and various cancer cells." (PMID 37063831, 2023). "Recently, it has been reviewed that IL6, TNFα, and IL1β play a central role in the toxicities of cancer immunotherapies." (PMID 36875156, 2023). "Further research in the field of colorectal cancer has unveiled insights into the influence of IL-6 on cancer cells." (PMID 37755304, 2023). "IL-6 is involved in immune surveillance, which is the process of the immune system recognizing and controlling cancer cells." (PMID 37892997, 2023). "Among multiple specific cytokines, IL-6 has one of the best proven pro-inflammatory effects in the pathogenesis of cancer." (PMID 37958406, 2023). "Many cancer-related cytokines, such as IL-1β, IL-6, and TNF-α, are elevated during oral infections due to LPS stimulation." (PMID 37249977, 2023). "We investigated the common genes that contributed to the change in the IL6/JAK/STAT3 and OXPHOS Cancer Hallmark pathways between the GH and SI rats and were reversed by JGT in the SI rats." (PMID 36980301, 2023). "The unadjusted univariate analyses showed increased risk of cancer with increasing plasma CRP, IL‐6, YKL‐40, CEA, CA 19‐9, CA‐125, PSA, age, former cancer diagnosis and PS ≥2." (PMID 36440611, 2023). "A significant positive correlation was observed between the LDH levels and the inflammatory cytokines VEGF-A, TNF-α, CCL2, and IL-6 levels within the Cancer TIF1-γ-DM group." (PMID 36357631, 2023). "The IFN-β, CXCL10, and IL-6 expression in MTHMS + L group elevated significantly both in cancer cells and BMDCs, evidencing the effective cGAS-STING pathway activation." (PMID 37221157, 2023). "Altogether, these data imply that IL-6 secreted by cancer cells undergoing genotoxic stress enables macrophages to gain an M2-like phenotype that possesses diminished anti-survival activities but augmented pro-migratory and invasive potentials." (PMID 37696858, 2023). "For example, elevated circulating TNF-α, IL-6, and GDF-15 have been reported to be associated with the severity of cachexia in cancer patients and mouse models." (PMID 37006254, 2023). "Regarding IL-6, as described in the article above, it is secreted by CAFs, which promote cancer cell dormancy by inducing autophagy." (PMID 37173977, 2023). "TGFβ has been shown to induce IL-6 expression in various types of cells, including lung fibroblasts, osteoblasts, and cancer cells." (PMID 37511415, 2023). "A prominent marker for cancer stem cells (CD44) is mediated by interleukin-6 (IL-6), which is a hub gene in UBC9 regulatory network." (PMID 37415251, 2023). "In the stomach, IL-6 plays an important role in inducing cancer cell invasion and maintaining gastric homeostasis at the same time." (PMID 37658354, 2023). "Distal CAFs from the cancer cells express high levels of proinflammatory cytokines such as IL-6, G-CSF, CXCL1, and LIF and are defined as iCAFs." (PMID 37065872, 2023). "Collectively this observation suggests that MDSC augments early generation of drug resistance of cancer cells by IL-6/STAT1 and IL-10/STAT3 axis." (PMID 38304256, 2023). "PaTu8988T amoeboid cells were shown to secrete high levels of interleukins [such as interleukin-1α (IL-1α), IL-5, IL-6, IL-7, IL-8, and IL-9], as well as several chemokines involved in cancer progression." (PMID 37851808, 2023). "IL-6 has also been shown to promote epithelial–mesenchymal transition (EMT) in several cancers through the altered expression of E- and N-cadherin, Vimentin, Snail, Twist, and others." (PMID 38067195, 2023). "It has been reported that upregulation of IL-6 in cancer cachexia leads to suppression of mTORC1 activation through AMP-activated protein kinase (AMPK) activation." (PMID 37217930, 2023). "As one of the most dysregulated signaling pathway in cancer, especially in breast cancer, many therapies targeting the IL6/JAK/STAT3 signaling pathway have been developed and studied." (PMID 37173331, 2023).
cancer (continued). "Dysregulated IL-6 signaling can contribute to the progression of pathological conditions, including cancer." (PMID 37809067, 2023). "Vimentin-stimulated DCs were also shown to have a decreased production of anti-cancer cytokines, IL-6 and IL-12." (PMID 36765706, 2023). "The pro-inflammatory cytokines IL-1β, IL-6, and IL-8 were two-fold elevated in contrast to TNFα, which appears to be a cytokine discriminating the inflammatory response in aging and cancer." (PMID 38003396, 2023). "Accordingly, IL-6 silencing renders cancer cells vulnerable to NK-LAAO-induced oxidative stress together with abrogating NK-LAAO-stimulated metastatic acquisition." (PMID 37385076, 2023). "In fibroblasts, CCL18 activates NF-κB pathway and produced a tremendous amount of IL-6 and IL-8, which induce the stemness and chemoresistance of cancer cells." (PMID 36418470, 2023). "TGFβ inhibits an IL1-induced phenotype and drives the fibroblast to acquire a myofibroblastic phenotype with less carcinogenesis, including reduced expression of markers supporting cancer stemness, such as IL6 and CXCL12." (PMID 36672697, 2023). "In SW620, higher expression level of Lon along with higher VEGF-A expression than that in SW480 was observed, implying that the secretion of VEGF-A and IL-6 from cancer cells is Lon-dependent." (PMID 35895109, 2023). "The expression levels of IL-6 and its family members can be useful to diagnose prognosis of relapse-free survival and recurrence in cancer patients." (PMID 36813833, 2023). "Cancer cells utilize several mechanisms to escape immune surveillance, including MHC loss and expression of immunosuppressive factors, such as IL-6, IL-10, TGF-β, prostaglandins, and Fas ligand." (PMID 36793738, 2023). "A recent review discussed the in-depth link between traditional circulating inflammatory markers, such as CRP, IL-6, and systemic inflammation in cancer patients." (PMID 36915049, 2023). "In OS TME, IL-6 is extensively produced from cancer-activated MSCs and promotes the expression of target genes related to cell differentiation, survival, apoptosis, proliferation, and stemness." (PMID 36831562, 2023). "According to several studies, MSC-secreted cytokines influence the IL-6/JAK2/STAT3 signaling pathway in cancer cells, which, in turn, can either stimulate or suppress tumor growth or trigger cancer cell apoptosis." (PMID 38132108, 2023). "IL-6 has been found to stimulate a macrophage phenotype change that promotes cancer by regulating the level of receptors for IL-4." (PMID 37760608, 2023). "The co-culture of monocytes with PSC, EC and PANC-1 cancer cells (PANC-1 4-culture) significantly increased the concentration of IL-6 when compared to any of the spheroids with a lower cellular heterogeneity." (PMID 37519820, 2023). "Τhese heterogeneous chemotherapy effects on TAM subsets can be explained by the indirect effects of platinum agents on macrophages via exposure to cancer cell-derived factors (e.g., IL-6) that promote protumor TAM conversion." (PMID 37545408, 2023). "IL-6 is another well-characterized pro-tumorigenic cytokine, which can be present in different stages of cancer development, from cell growth, EMT, migration, and invasion, to metastasis." (PMID 37511415, 2023). "A potentially fruitful alternative avenue for small-molecule inhibitors are cancer-specific protein–protein interactions, for example on the IL-6/JAK/STAT axis." (PMID 37509339, 2023). "Accordingly, supernatant secreted from MDSCs induces a surge of receptor expression for IL-6, IL-10 and IL-1β in cancer cells." (PMID 38304256, 2023). "In conclusion, plasma CRP, IL‐6 and YKL‐40 alone or combined cannot be used to identify patients with cancer, but high levels were associated with poor prognosis." (PMID 36440611, 2023). "Tipifarnib-induced decreases in NF-κB and TGF-β expression and the IL-6 level inhibit inflammation–cancer feedback." (PMID 37511305, 2023).